FEN1 (flap structure-specific endonuclease 1)
Diseases named in the same sentence as FEN1 in open-access papers (continued):
Sharing a sentence is not in itself a finding about the gene and the disease.
prostate carcinoma (continued). "Although previous studies have indicated that FEN1 promotes cell proliferation in prostate cancer, the role of FEN1 in the prostate cancer progression, metastasis and drug resistance remains unclear." (PMID 37326412, 2023). "Notably, a positive correlation between AR and FEN1 expression has likewise been observed in prostate cancer." (PMID 37326412, 2023). "Second, whether phosphorylation and ubiquitination of FEN1 influences survival and cell cycle changes in prostate cancer cells remains unclear." (PMID 37326412, 2023). "Taken together, these results indicate that AR knockdown may enhance the chemosensitivity of prostate cancer cells by downregulating FEN1 through the ERK/ELK1 signalling pathway." (PMID 37326412, 2023). "In this study, we confirmed that targeting AR could enhance the sensitivity of DTX to prostate cancer cells by upregulating FEN1 expression." (PMID 37326412, 2023). "When AR was knocked down in prostate cancer cells, FEN1 expression was also downregulated." (PMID 37326412, 2023). "In the present study, both in vivo and in vitro experiments showed that FEN1 inhibited DTX‐induced apoptosis and reversed G1/S phase arrest caused by DTX in prostate cancer, which eventually promoted tumour growth; knocking down FEN1 yielded the opposite results." (PMID 37326412, 2023). "Furthermore, AR overexpression increases FEN1 protein production in prostate cancer cells." (PMID 37326412, 2023). "Therefore, we speculate that AR enhances the DDR of prostate cancer cells by regulating FEN1 expression, which in turn promotes tumour growth and resistance to ADT or chemotherapy." (PMID 37326412, 2023). "We hypothesised that FEN1 would serve as a therapeutic target for prostate cancer." (PMID 37326412, 2023). "Therefore, we speculate that FEN1 knockdown leads to unrepaired DNA damage induced by DTX in prostate cancer cells, which results in cell cycle arrest at the S phase and increased cell apoptosis." (PMID 37326412, 2023). "Urbanucci found that nuclear FEN1 staining was stronger in CRPC than in standard PC samples, and that FEN1 can promote prostate cancer cell growth." (PMID 37326412, 2023). "Flap endonuclease 1 (FEN1) is highly upregulated in prostate cancer and promotes the growth of prostate cancer cells." (PMID 37326412, 2023). "In addition, FEN1 overexpression reduced the proportion of S phase cells (20.47 ± 1.65%) compared to the LNCaP‐FEN1‐KD group.The results indicated that DTX induced S‐phase arrest in prostate cancer cells, which could be partially reversed by FEN1 overexpression." (PMID 37326412, 2023). "In conclusion, AR knockdown results in the inactivation of the ERK/ELK‐1 signalling pathway that, in turn, leads to the downregulation of FEN1 and improves the DTX sensitivity of prostate cancer cells." (PMID 37326412, 2023). "Taken together, these findings indicated that FEN1 was related to cell cycle activity and MAPK pathway in prostate cancer." (PMID 37326412, 2023). "We confirmed the regulatory effect of AR on FEN1, pho‐ERK1/2 and pho‐ELK1 in prostate cancer cells." (PMID 37326412, 2023). "First, we still do not know whether AR is involved in the regulation of FEN1 phosphorylation or ubiquitin in prostate cancer." (PMID 37326412, 2023).
glioblastoma (4 papers, 2006 to 2021). The most malignant astrocytic tumor (WHO grade IV). "While exposure to acute hypoxia decreased expression of BER genes MTH1, OGG1 and FEN1, we did not observe differences in the expression of these genes between anoxia-tolerant and oxic control NCI-H460 lung or T98G glioblastoma cancer cells in acute hypoxic conditions." (PMID 34831264, 2021).
melanoma (4 papers, 2020 to 2025). A malignant, usually aggressive tumor composed of atypical, neoplastic melanocytes. "In melanoma brain metastases, heterozygous copy number loss of HR and SSB repair, but no mismatch repair-associated genes, was found, which from the most prevalent genes were APTX, FEN1, GTF2H5, DNA2, MUS81 and TOP3A." (PMID 34885093, 2021). "Furthermore, one of the catechol-based ERCC1-XPF inhibitors (13 compounds) showed higher activity in NER and selectivity against deoxyribonuclease I and Flap structure-specific endonuclease 1 (FEN-1) in A375 melanoma cells, resulting in improved cisplatin activity." (PMID 37062547, 2023). "Additionally, one of the investigated catechol-based inhibitors of ERCC1-XPF (13 compound) displayed high activity in NER and selectivity against deoxyribonuclease I and Flap structure-specific endonuclease 1 (FEN-1), which resulted in enhanced cisplatin activity in A375 melanoma cells." (PMID 32370233, 2020).
Breast tumor (3 papers, 2015 to 2025). "The relative gene expression analysis of seven PGC-associated genes, including CCNB1, CCNB2, FEN1, MCM4, PTTG1, RACGAP1, and UBE2C, was conducted on the samples of breast tumors compared to healthy mammary tissues." (PMID 41009526, 2025). "Previously, we have shown that low RECQL breast tumors were significantly associated with low PARP1, BRCA1 negative, low RAD51, low ATM, low nuclear pChk1, low nuclear Chk2, low XRCC1, low FEN1, low SMUG1, and low DNA-PKcs expression." (PMID 38134458, 2023). "Breast tumor stromal cells exhibit a distinct expression profile, marked by the expression of genes such as FEN1, RACGAP1, and MCM4, which may delineate their functional identity." (PMID 41009526, 2025). "For overall 249 breast tumor samples (p = 0.0007), 211 of ER+ subgroups (p = 0.005), 34 of ER- subgroups (p = 0.03), 20 of ER-LN- subgroups (p = 0.007) all showed an inverse correlation of FEN1 gene expression with DFS." (PMID 25885449, 2015).
Fanconi anemia (3 papers, 2013 to 2020). Fanconi anemia (FA) is a hereditary DNA repair disorder characterized by progressive pancytopenia with bone marrow failure, variable congenital malformations and predisposition to develop hematological or solid tumors. "This novel regulation of FEN1 by FANCA is impaired in pathogenic FANCA mutants thus making the novel interaction physiologically relevant to Fanconi anemia." (PMID 24349332, 2013). "To evaluate whether stimulation of FEN1 by FANCA is physiologically relevant to Fanconi anemia, we created 5 more FANCA point mutations and purified them to near homogeneity." (PMID 24349332, 2013). "These are likely a result of the accumulation of aberrant replication forks, that accumulate as a consequence of a failure in Okazaki fragment maturation, as inhibition of FEN1 is toxic in cells disrupted for the Fanconi anemia pathway and post-replication repair." (PMID 28628639, 2017). "Finally, FEN1 appears to be required for the repair of damage induced by olaparib and cisplatin within the Fanconi anemia pathway, and may play a role in the repair of damage associated with its own disruption." (PMID 28628639, 2017). "More importantly, all six pathogenic FANCA mutant proteins we tested were defective in this interaction to different degrees, indicating that the interaction between FEN1 and FANCA physiologically contributes to the pathogenesis of Fanconi anemia." (PMID 24349332, 2013). "Similarly, we demonstrated that FEN1 inhibition activated the ATM checkpoint signalling pathway, the phosphorylation of histone H2AX and the ubiquitination of FANCD2, suggesting the initiation of the Fanconi anemia (FA) pathway." (PMID 28628639, 2017).
Fuchs endothelial corneal dystrophy (3 papers, 2014 to 2019). Fuchs endothelial corneal dystrophy (FECD) is the most frequent form of posterior corneal dystrophy (see this term) and is characterized by excrescences on a thickened Descemet membrane (corneal guttae), generalized corneal edema, with gradually decreased visual acuity. "Our findings suggest that the g.61564299G>T and c.–441G>A polymorphisms in the FEN1 gene may modulate the risk of keratoconus and Fuchs endothelial corneal dystrophy." (PMID 25153632, 2014). "Distribution of genotypes and alleles of the c.–441G>A (rs174538) and the g.61564299G>T (rs4246215) polymorphisms of the FEN1 gene and odds ratio (OR) with 95% confidence interval (95% CI) in patients with Fuchs endothelial corneal dystrophy (FECD) and controls." (PMID 25153632, 2014). "Similarly, variants in ZEB1, COL8A2, TCF4, FEN1, AGBL1, and LOXHD1 all cause Fuchs endothelial corneal dystrophy (FECD), while the age of onset may vary." (PMID 31555324, 2019).
head and neck squamous cell carcinoma (3 papers, 2017 to 2021). A squamous cell carcinoma that arises from any of the following anatomic sites: lip and oral cavity, nasal cavity, paranasal sinuses, pharynx, larynx, and salivary glands. "Previous studies based on GWAS approach have shown that FEN1 was significantly associated with ESCC and head and neck squamous cell carcinoma (HNSCC)." (PMID 29348864, 2017).
liver cirrhosis (3 papers, 2019 to 2022). "Association analysis showed that FEN1 expression significantly correlated with tumor size (P = 0.047) and metastasis status (P = 0.013), but did not correlate with patient gender, age, hepatitis B infection status, liver cirrhosis or tumor stage." (PMID 31402791, 2019). "Additionally, HCC tissues had significantly higher FEN1 levels than HCC precursor status or liver cirrhosis tissues, suggesting the oncogenic role of FEN1 in HCC." (PMID 35173534, 2022). "FEN1 expression did not significantly correlated with gender, age, tumor multiplicity, TNM stage, pathological grade, HBsAg, liver cirrhosis or serum alpha-fetoprotein (AFP) (P > 0.05)." (PMID 31534853, 2019).
lymph node metastasis (3 papers, 2015). "Interestingly, we saw a similar significant correlation between the synergic effect of FEN1 and RAD54B and lymph node metastasis and poor patient survival in our study." (PMID 26431531, 2015).
triple-negative breast carcinoma (3 papers, 2020 to 2025). An invasive breast carcinoma which is negative for expression of estrogen receptor (ER), progesterone receptor (PR), and human epidermal growth factor receptor 2 (HER2). "Additionally, a structure specific for flap endonuclease 1 (FEN1) was observed to be induced by PAC in triple-negative breast-cancer cells." (PMID 37298600, 2023). "Five other members belonging to the family of homologous recombination repair genes were upregulated by PAC in triple-negative breast-cancer cells (RAD54L, XRCC3, RAD51D, FEN1, and TOP3A) but only RAD54L is common in both types of cell lines (MCF-7 and MDA-MB-231)." (PMID 37298600, 2023).
adenoma (2 papers, 2013 to 2022). A neoplasm arising from the epithelium. "We observed that the minor alleles of the FEN1 SNPs rs509360 and rs108499 were associated with a two-fold increased and decreased risk of adenoma, respectively, among Asian-Pacific Islanders." (PMID 23951112, 2013). "Finally, the FEN1 rs108499 SNP also modified the association between smoking pack-years and adenoma risk (interaction pgene = 0.039, interaction ppathway = 0.507)." (PMID 23951112, 2013). "However, one of these six tagSNPs, FEN1 rs108499, was found to modify the effects of smoking on adenoma risk." (PMID 23951112, 2013).
brain tumors (2 papers, 2016 to 2017). "Previous studies demonstrated that FEN1 overexpression is common in breast, prostate, lung, and brain tumors, predicting FEN1 might be a marker of tumor progression for many types of tumors." (PMID 27801669, 2016).
breast ductal carcinoma in situ (2 papers, 2015 to 2021). "This study aims to assess the role of FEN1 in breast ductal carcinoma in situ (DCIS)." (PMID 34117958, 2021). "Due to the controversy of FEN1 roles in cancer progression and behaviour and lack of studies describing its role in breast ductal carcinoma in situ (DCIS), we have hypothesised that FEN1 expression in DCIS plays a role in the disease progression." (PMID 34117958, 2021).
colorectal adenoma (2 papers, 2013 to 2022). An adenoma that arises from the colon or rectum. "We observed statistically significant associations between colorectal adenoma risk and polymorphisms in the FEN1 gene (two tagSNPs) and NTHL1 gene (one tagSNP) among Asian-Pacific Islanders, and the APEX1 gene among African-Americans (one tagSNP)." (PMID 23951112, 2013). "However, among Asian-Pacific Islanders we observed two SNPs in FEN1 and one in NTHL1, and among African-Americans one SNP in APEX1 that were associated with colorectal adenoma risk." (PMID 23951112, 2013).
Ewing sarcoma (2 papers, 2020 to 2025). A small round cell tumor that lacks morphologic, immunohistochemical, and electron microscopic evidence of neuroectodermal differentiation. "We experimentally validated that FEN1 was upregulated in Ewing sarcoma cell lines compared to IMR90." (PMID 32290418, 2020). "This led us to hypothesize FEN1 could be important for resolving R-loops in Ewing sarcoma and, consequently, maintaining high proliferation rates." (PMID 32290418, 2020). "Furthermore, according to the depmap database, FEN1 is among the top dependencies for Ewing sarcoma." (PMID 32290418, 2020). "More importantly, unlike in IMR90, FEN1 inhibition led to further accumulation of R-loops in Ewing sarcoma cells." (PMID 32290418, 2020). "Furthermore, the chemical inhibition of FEN1 resulted in severe toxicity in Ewing sarcoma, but not in IMR90." (PMID 32290418, 2020).
gallbladder cancer (2 papers, 2015 to 2018). "Haplotype analyses showed that the FEN1 A-69G4150, G-69G4150 and G-69T4150 haplotypes were associated with a significantly increased risk of gallbladder cancer." (PMID 26668074, 2015). "Significantly increased association with gallbladder cancer was observed for subjects with both the FEN1-69G > A GA (OR = 1.73, 95% CI = 1.02–2.63) and the FEN1-69G > A GG (OR = 2.29, 95% CI = 1.31–3.95)." (PMID 26668074, 2015). "FEN1 SNPs were genotyped using the polymerase chain reaction-restriction fragment length polymorphism method in blood samples from 341 gallbladder cancer patients and 339 healthy controls." (PMID 26668074, 2015). "Significantly increased association for gallbladder cancer was observed for subjects with both the FEN1-4150T GT(OR = 1.93, 95% CI = 1.04–2.91) and the FEN1-4150T GG(OR = 2.56, 95% CI = 1.37–5.39)." (PMID 26668074, 2015). "We assessed the association of two functional FEN1 SNPs and their haplotypes with gallstone and gallbladder cancer risk in a Chinese population." (PMID 26668074, 2015). "In this study, we found significantly increased gallbladder cancer risk among carriers of the FEN1 -69G and 4150G alleles and the G-69G4150 haplotype when compared with carriers of the -69A and 4150T alleles, the G-69T4150 T alleles or the G-69T4150 haplotype." (PMID 26668074, 2015). "Our data confirmed that FEN1 polymorphisms and haplotypes were associated with elevated gallbladder cancer risk, and that gallstones synergistically increased this gallbladder cancer risk." (PMID 26668074, 2015). "In conclusion, this study revealed firstly that FEN1 polymorphisms and haplotypes are associated with gallbladder cancer risk." (PMID 26668074, 2015). "In this population, we found a significantly increased gallbladder cancer risk among carriers of the FEN1 -69G and 4150G alleles and the G-69G4150 haplotype compared with carriers of the -69A and 4150T alleles, the G-69T4150 T alleles or the G-69T4150 haplotype." (PMID 26668074, 2015). "To determine whether the FEN1 allele contributed to increased association of gallbladder cancer, we examined the prevalence of FEN1 alleles in gallbladder cancer cases versus controls." (PMID 26668074, 2015). "A significant trend towards increased association with gallbladder cancer was observed with potentially higher-risk FEN1-69G > A genotypes (P < 0.001, χ2 trend test) and FEN14150G > T (P < 0.001, χ2 trend test) in gallstone presence but not in gallstone absence (P = 0.81, P = 0.89, respectively)." (PMID 26668074, 2015). "The current study demonstrated that the interaction of genetic factors and the environment, in this case the interaction of FEN1 polymorphisms and gallstones, could synergistically increase the risk of gallbladder cancer." (PMID 26668074, 2015). "The role of FEN1 genetic variants on gallstone and gallbladder cancer susceptibility is unknown." (PMID 26668074, 2015). "To determine the relationship between FEN1 genotype and gallbladder cancer by exposure to gallstone, we stratified study subjects by FEN1 genotype and gallstone status." (PMID 26668074, 2015). "The distribution of FEN1-69G > A genotypes among controls(AA, 20.6%; GA, 47.2% and GG 32.2%), the frequencies of the 3 genotypes among gallbladder cancer were AA,11.1%-; GA,48.1%- and GG, 40.8%." (PMID 26668074, 2015). "To this end, we have studied the association of flap endonuclease 1 (FEN1; MIM 600393) SNPs with gallbladder cancer." (PMID 26668074, 2015). "In the meantime, the distribution of FEN1 -4150T genotypes among controls(TT, 21.8%;GT, 49.3% and GG 28.9%), the frequencies of the 3 genotypes among gallbladder cancer were TT,12.9%-; GT, 48.4% and GG 38.7%." (PMID 26668074, 2015). "The allelic frequencies of FEN1 -69A and -4150T were 0.378 and 0.373, respectively, among the 339 healthy controls, and 0.301 and 0.296, respectively, among the 341 gallbladder cancer cases." (PMID 26668074, 2015).
gallbladder cancer (continued). "Therefore, the complicated genetic models of the FEN1 genotypes/diplotypes for gallbladder cancer could not be accurately matched with controls defined by the presence of gallstones or gallstones of varying size." (PMID 26668074, 2015).
invasive breast carcinoma (2 papers, 2019 to 2021). A carcinoma that infiltrates the breast parenchyma. "Some studies showed that FEN1 is upregulated in invasive breast cancer (IBC) compared to normal breast tissue." (PMID 34117958, 2021). "Expression of FEN1 protein was evaluated in a large (n = 1015) well-characterised cohort of DCIS, comprising pure (n = 776) and mixed (DCIS coexists with invasive breast cancer (IBC); n = 239) using immunohistochemistry (IHC)." (PMID 34117958, 2021). "There was no significance of DNA promoter methylation between invasive breast cancer and normal breast tissues in 4 upregulated hub genes (MAD2L1, FEN1, CDKN3, CCN2)." (PMID 31777591, 2019).
ovarian tumor (2 papers, 2021 to 2022). "In addition to the predictive significance of BRCA2/FEN1 co-expression, the data also suggests that a proportion of ovarian tumors with low BRCA2 may also overexpress FEN1." (PMID 33919707, 2021). "Moreover, we observed a negative correlation between miR-4324 and FEN1 expression in ovarian tumor tissues." (PMID 35246224, 2022).
viral infection (2 papers, 2021). "So far, knowledge on the utilization of the structure-specific endonuclease FEN1 during viral infections is limited." (PMID 33770148, 2021). "This emphasizes that blocking enzymatic activities of DNA repair proteins such as FEN1 may represent novel therapeutic opportunities for the treatment of viral diseases." (PMID 33770148, 2021). "So far, knowledge on the role of FEN1 during viral infections is limited." (PMID 33770148, 2021). "However, we are not able to rule out that early or late proteins, which were severely decreased during mutant virus infection, might additionally influence FEN1 phosphorylation." (PMID 33770148, 2021).
Werner syndrome (2 papers, 2017 to 2018). "In addition, genes that cause progeria were also included, specifically UBE2I for Progeria and FEN1 and RECQL for Werner syndrome, suggesting a role for the common JAGs to hamper the premature aging." (PMID 29449671, 2018).
xeroderma pigmentosum group (2 papers, 2012 to 2022). "The excision repair cross complementing group 5 (ERCC5) gene, also known as the xeroderma pigmentosum group G (XPG) gene, is a member of the flap structure-specific endonuclease 1 (FEN1) family and encodes a protein of 1186 amino acids." (PMID 22815677, 2012).